IL7R (interleukin 7 receptor)
Diseases named in the same sentence as IL7R in open-access papers (continued):
Sharing a sentence is not in itself a finding about the gene and the disease.
leukemia (58 papers, 2011 to 2026). A malignant (clonal) hematologic disorder, involving hematopoietic stem cells and characterized by the presence of primitive or atypical myeloid or lymphoid cells in the bone marrow and the blood. "To further immunophenotypically define these preLSCs, we assessed the expression of hematopoiesis-regulating receptors, such as Il-7r, Notch1, Kit, and Flt3, which have been implicated in leukemia development." (PMID 39849166, 2025). "These analyses showed that human IL7R mutations collaborated with Myc to accelerate leukemia onset significantly." (PMID 35581375, 2022). "Here, we provided the first direct evidence, comparing Myc versus Myc + IL7Rmut leukemias, that IL7R mutational activation increases LPC frequency." (PMID 35581375, 2022). "Homozygous IL7R mutant mice, which show maximal signaling, develop very rapid, fatal leukemia with a trend for lower mutational burden, thereby illustrating the importance of IL-7R signaling upregulation in driving leukemogenesis." (PMID 34907175, 2021). "Considering that mutations in the IL-7Rα gene have been found in nearly 10% of pediatric leukemia cases, this pathway represents a fruitful opportunity for the development of an immunotherapy modality to target." (PMID 34830969, 2021). "Our results demonstrate that IL7R gain-of-function mutation initiates leukemia by causing a pre-leukemic stage in B cell precursors with evidence of self-renewal activity." (PMID 34907175, 2021). "IL7 signaling is critical for lymphopoiesis and, in the context of T-ALL, it plays a role in activation of the JAK/STAT5 and PI3K/Akt/mTOR pathways, with 10% of patient leukemia samples containing activating IL7r mutations." (PMID 34394130, 2021). "Using CX-4945, we demonstrated that CK2 pharmacological inhibition impaired JAK/STAT5 and PI3K/Akt signaling pathway activation triggered by IL-7 or by IL7R mutational activation and consequently impaired the pro-leukemia effects of IL-7." (PMID 32471246, 2020). "In leukemia, somatic mutations in IL7R are prevalent in 10% of pediatric T-ALL cases and gain-of-function mutations are reported in both T-ALL and B-ALL." (PMID 32085659, 2020). "To demonstrate the efficacy of ruxolitinib in leukemia driven by an IL7Rα mutation, we performed therapeutic studies in Rag1−/− mice engrafted with D1_hIL7RP1." (PMID 29854301, 2018). "Taken together, this indicates that ruxolitinib, even as a monotherapy, can slow the progression of leukemia with an IL7Rα mutation." (PMID 29854301, 2018). "In fact, mutations affecting the activity of PRC2 complex are present in 40% of ETP-ALL patients and highly associated with activating mutations of the IL7R/JAK/STAT pathway which gives relevance to using human LOUCY ETP-ALL cell line to model to study the biology of ETP-ALL leukemia." (PMID 36229595, 2022). "Our data implicate Ikaros/IL7R/SH2B3 signaling in oncogenesis of high-risk leukemia." (PMID 27322554, 2016). "The downregulation of IL7R in T-ALL/T-LBL might cause a rise in tyrosine kinase activity inside the leukemia cells, leading to continuous stimulation of cytokine receptor signaling pathways and ultimately culminating in significant impairments in T-cell function." (PMID 38464517, 2024). "Interestingly, we observe the upregulation of Lck in IL7R mutant leukemias, suggesting the possibility that Src-family kinase inhibitors may be of relevance in cases with IL7R mutation." (PMID 35581375, 2022). "However, leukemia establishment associated with marked IL-7R signaling upregulation." (PMID 34907175, 2021). "This switch in growth factor dependency was confirmed in vivo, where the acquired IL-7-independence of leukemia cells was sufficient to sustain the expansion of leukemic blasts in NSG recipients treated with IL-7R-blocking antibody." (PMID 38519798, 2024).
leukemia (continued). "One of the most recent investigations, based on a loss-of-function approach, formally demonstrated that the oncogenic programme of NOTCH1 and leukemia-initiating cells (LIC) activity were dependent on IL7R expression." (PMID 36624522, 2023). "IL7R exhibits antitumor effects in leukemia, prostate cancer, and gliomas, but exhibits tumor promotion in T-cell acute lymphoblastic leukemia and bladder cancer." (PMID 37381714, 2023). "Many studies on hematologic diseases prove that the IL7/IL7R axis is also an important factor in the development of leukemia." (PMID 37381714, 2023). "STAT5, PI3K/Akt/mTOR and MEK/Erk pathways are activated by IL-7R-mediated signaling in healthy lymphocytes and leukemia cells." (PMID 35581375, 2022). "As expected, mutant IL7R-driven leukemias exhibited elevated IL-7R-mediated signaling, indicated by high expression of common STAT5 downstream target genes." (PMID 35581375, 2022). "In the present studies, we showed that IL7R mutation collaborates with Myc in accelerating T-ALL onset and decreasing apoptosis of leukemia cells." (PMID 35581375, 2022). "Overall, our studies demonstrate that IL7R mutation is sufficient to trigger T-ALL development in zebrafish, while also cooperating with Myc to accelerate disease onset and increase leukemia propagating cell frequency." (PMID 35581375, 2022). "Characterizing these mechanisms and how they impact the sensitivity of particular lymphoid precursors to transformation will be of major importance for the understanding of how IL7R partakes in human leukemia development." (PMID 35581375, 2022). "To address the ability of mutant IL7R to cooperate with Myc to accelerate the time to leukemia onset, we next used a mosaic transgenic approach to create zebrafish T-ALLs." (PMID 35581375, 2022). "To characterize mutant IL7R-driven leukemias deeper, we next confirmed the lymphoblast morphology of leukemic cells and their T-cell phenotype, as confirmed by qRT-PCR analysis." (PMID 35581375, 2022). "Human marrow stromal cells, endothelial cells, normal human intestinal epithelial cells, and several malignant tumor cell lines containing breast cancer, melanoma, leukemia, lung cancer and cutaneous T cell lymphoma were all found to express IL-7Rα." (PMID 36142322, 2022). "As expected, RNAseq analysis confirmed qPCR results and showed that mutant IL7R-derived leukemias were bona fide T-ALLs." (PMID 35581375, 2022). "We confirmed that pre-leukemia cells displayed cell-autonomous upregulation of IL-7R-mediated signaling, measured by phospho-STAT5 and phospho-S6 levels." (PMID 34907175, 2021). "The relatively long median latency for leukemia development in the IL7R mutant heterozygous mice is also consistent with the fact that Ph-like ALL is predominant in older patients." (PMID 34907175, 2021). "Notch1 activates IL7r transcription in human hematopoietic progenitors, as well as in murine leukemia cells." (PMID 34394130, 2021). "Accordingly, maximal signaling drives full penetrance and early leukemia onset in homozygous IL7R mutant animals." (PMID 34907175, 2021). "Although IL7R mutations are frequently subclonal in human ALL, indicating they occur late in leukemia development, there are cases of Ph-like B-ALL where IL7R mutant allele frequency is compatible with IL7R mutation being the initiating lesion." (PMID 34907175, 2021). "Altogether, our data indicate that IL7R mutant-driven leukemias are either PAX5 P80R or Ph-like, in accord with these subtypes being enriched within mutant IL7R patients." (PMID 34907175, 2021). "Leukemia developed with very rapid kinetics (median latency of 12 weeks) and full penetrance at 31 weeks, and displayed highest IL-7R-mediated signaling levels." (PMID 34907175, 2021). "Further studies identified patients with IL7R-high, LNK-low, high-risk B-ALL associated with Ikaros dysfunction, implicating IL7R/LNK/Ikaros in the oncogenesis of high-risk leukaemia." (PMID 35056081, 2021).
leukemia (continued). "In vivo, IL-7R signaling pathway target genes were mildly upregulated in pre-leukemia cells as compared to normal controls." (PMID 34907175, 2021). "B12 is able to inhibit IL-7-dependent and mutant-dependent IL-7R-mediated signaling and induce leukemia cell death." (PMID 32849527, 2020). "Treatment of recipient mice with anti-IL7R antibody significantly delayed leukemia onset and led to significant prolongation of the survival time of the respective animals." (PMID 32581241, 2020). "In contrast, anti-IL7R antibody significantly delayed leukemia onset in vivo and led to a significantly expanded survival time of the respective animals." (PMID 32581241, 2020). "Within the B-ALL molecular subtypes, IL7R expression values were higher in the BCR/ABL1, ETV6/RUNX1, TCF3/PBX1, and KMT2A(MLL) high-risk leukemia subtypes." (PMID 32085659, 2020). "More importantly, up to 10% of T-ALL cases harbor activating mutations in genes encoding different molecular effectors downstream of IL-7R signaling, including JAK1, JAK3 and STAT5B, reinforcing the role of IL-7R in leukemia cell proliferation." (PMID 33081391, 2020). "Here, we explored alternative, antibody-based strategies to directly target the IL-7R in leukemia cells." (PMID 30850736, 2019). "Considering the limited amount of IL-7 available in the bone marrow microenvironment, cells expressing a mutant IL7Rα would override the population of normal cells that express the wild type IL7Rα, contributing to leukemia progression." (PMID 31817502, 2019). "Then we quantified LSCs (IL7Rα-Lin−cKit+Sca1−21) in the leukemia-bearing mice following OSKM induction." (PMID 31811153, 2019). "Consistently, the combined treatment of JAK2 inhibitor ruxolitinib and venetoclax reduced leukemia burden in an IL7R mutant T-ALL mouse model in vivo." (PMID 31226848, 2019). "There is a rising interest in the potential of anti-IL-7Rα antibodies for treatment of autoimmune, chronic inflammatory diseases, and, more recently, also leukemia." (PMID 30850736, 2019). "Mutations in IL7R, FBXW7, and NOTCH1 were specific to myeloid-T MPAL and T-ALL, suggesting a strong functional role of these genes in T cell lineage leukemia." (PMID 29991687, 2018). "Therefore, targeting BCL-2 could also be beneficial in leukemias with IL7Rα mutations." (PMID 29854301, 2018). "JAK1 is associated with IL-7Rα, leading us to evaluate efficacy of ruxolitinib, a potent JAK1 inhibitor in a leukemia model driven by mutant IL-7Rα." (PMID 29854301, 2018). "Extended survival of the transplanted NOD/SCID in the A7R34-treated animals was seen, indicating that enhanced Il7r levels and its downstream signalling is contributing to the increased leukaemia-initiating capacity of the Zeb2-overexpressing tumours." (PMID 25565005, 2015). "All CAR-expressing T cells also had increased glycolysis above that of unmodified T cells, which suggests that the IL7R pathway–activated T cells may have improved and effective antitumor activity in the metabolically unfavorable leukemia microenvironment." (PMID 39186002, 2024). "However, less frequently mutated genes IL7R, XBP1, and TOX also demonstrated high cancer effects, suggesting pivotal roles in the development of leukemia when present." (PMID 38928295, 2024). "To determine whether Phf6 deficiency suppresses AML progression by decreasing LSCs (leukemia stem cells) number and activity, we analyzed the frequency and absolute number of c-Kit+ and L-GMP (Lin− c-Kit+ IL-7R− Sca-1− CD16/32+ CD34+) LSCs in BM and spleen." (PMID 38336746, 2024). "We next performed a transcriptomic characterization of primary IL7R mutant leukemias." (PMID 35581375, 2022). "Our current studies indicate that ectopic expression of wild type IL-7Rα is not sufficient to promote leukemia development in zebrafish, whereas gain-of-function mutations lead to the development of T-ALL, but not B-ALL." (PMID 35581375, 2022). "Myc + IL7Rmut leukemias also displayed upregulation of IL-7R-mediated signaling." (PMID 35581375, 2022).
leukemia (continued). "A higher degree of leukemia polyclonality indicates stronger oncogenic potential and transformation of larger pools of initiating cells, which is in accordance with the fact that mutant IL7R accelerated disease onset in Myc-induced T-ALLs." (PMID 35581375, 2022). "Notably, leukemias derived from the combination of Myc and mutant IL7R exhibit high basal IL-7R-mediated signaling activation and display higher frequency of leukemia propagating cells (LPCs) than T-ALLs derived from Myc alone." (PMID 35581375, 2022). "Taking all this together, a clear leukemia-initiating effect of constitutively active IL-7Rα could be observed in different mouse models as well as in human hematopoietic progenitors, with similarities to Ph-like and/or PAX5 P80R BCP-ALL subtypes." (PMID 35294722, 2022). "To evaluate whether IL7R modulates leukemia propagating cell (LPC) frequency, we next analyzed the impact of mutant IL7R on the self-renewal potential of Myc-induced T-ALL cells." (PMID 35581375, 2022). "Moreover, limiting-dilution cell transplantation experiments reveal that activated IL-7R signaling increases the overall frequency of leukemia propagating cells." (PMID 35581375, 2022). "Moreover, the intravenous injection of IL-7Rα p.L242-L243insNPC-expressing D1 cells, as well as IL-7Rα p.L242-L243insGC- and IL-7Rα p.IL241–242TC-positive Arf-/- thymocytes into Rag-/- mice resulted in leukemia development." (PMID 34066732, 2021). "Interestingly, blockade of these cytokines or their respective receptors has shown promising clinical outcomes in several types of cancers, including leukemia (anti-IL-7Rα), lung (anti-IL-1β) and skin (anti-TGF-β1) cancers." (PMID 34298791, 2021). "If so, maximal IL-7R signaling should drive faster leukemia development." (PMID 34907175, 2021). "Although some B-ALL cases harbor clonal IL7R gain-of-function mutations, suggesting that IL7R activation can be an early event in leukemia development, there is no formal evidence that IL7R drives B-ALL." (PMID 34907175, 2021). "Like normal T and B progenitors, most T-ALL and B-ALL cells express functional receptors for IL-7 (IL-7R) which are able to promote leukemia survival and proliferation both in vitro and in patient- derived xenograft assays, suggesting a role for IL-7R/IL-7 pathway in ALL progression." (PMID 34026651, 2021). "Here, the authors show interleukin 7 receptor (IL7R) signaling to contribute to this resistance mechanism, and that targeting the IL7R pathway may suppress incurable drug-resistant leukemia forms." (PMID 32581241, 2020). "Importantly, treatment with anti-IL7R antibodies prevents leukemia development in xenotransplantation models using patient-derived Ph+ ALL cells." (PMID 32581241, 2020). "Moreover, studies in vitro showed that leukemia blasts from a majority of the patients (~ 70%) display IL-7R and that IL-7 promotes their survival and proliferation." (PMID 30850736, 2019). "Although mutations in IL-7Rα do not predict poor clinical outcome, many subsets of leukemia with mutations in JAK/STAT pathway components have a high risk of relapse and poor prognosis." (PMID 29854301, 2018). "Next, Meijerink and colleagues extended their analyses to 146 leukemia samples, for which they determined the mutational status of a selected panel of genes required for IL7R–RAS–MAPK–AKT signaling (IL7Ra, JAK1, JAK3, NF1, NRAS, KRAS, and AKT) by PCR-based Sanger sequencing." (PMID 27997538, 2016). "We then further tested whether clinically relevant inhibitors of the IL7R signaling pathway affected the prednisolone sensitivity of primary leukemia cells isolated from 11 pediatric T-ALL patients at diagnosis." (PMID 27997540, 2016). "Interestingly, T-ALLs that harbor mutations in IL7R–RAS–MAPK–AKT signaling were associated with specific molecular genetic subtypes, including immature, TLX1, TLX3-rearranged, or HOXA-activated leukemias." (PMID 27997538, 2016).
leukemia (continued). "Since MEF2C is normally downregulated during the ETP stage, prolonged or enhanced MEF2C expression may cause supraphysiological IL-7R signaling and BCL2 expression that contributes to the arrest, survival, and enhanced growth of ETP cells resulting in leukemia." (PMID 35536646, 2022). "Overexpression of IL-7R also leads to potential thymocyte self-renewal and thymic hyperplasia related to proliferation of T cell precursors, which in turn infiltrates the lymph nodes, spleen, and bone marrow, ultimately resulting in fatal leukemia in a dose-dependent manner." (PMID 36142322, 2022). "Here, we demonstrate that lymphoid-restricted mutant IL7R, expressed at physiological levels in conditional knock-in mice, establishes a pre-leukemic stage in which B-cell precursors display self-renewal ability, initiating leukemia resembling PAX5 P80R or Ph-like human B-ALL." (PMID 34907175, 2021). "Therefore, we tested whether direct targeting of the IL7R using specific monoclonal antibodies may interfere with its function in leukemia." (PMID 32581241, 2020). "In addition, development of leukaemia with a distinct immature phenotype (aberrant expression of CD44, myeloid markers, and intracellular CD3), similar to that observed in ETP-ALL patients, was detected in mice transplanted with Il-7r-mutated thymocytes." (PMID 31792348, 2020). "Moreover, these mAb chimeras inhibit IL-7R signaling at low IL-7 concentrations, mediate antibody-dependent cell mediated cytotoxicity in vitro and are effective in controlling established and relapsing leukemia in vivo." (PMID 32849527, 2020). "B cells develop properly by combining signals from IL7R and pre-BCR; however, when these signals are disrupted in B-ALL, they lead to the sustained growth of leukemia and actively drive leukemogenesis." (PMID 40709996, 2025). "The IL7R and pre-BCR signaling pathways intersect at several key points, affecting B cell development and leukemia." (PMID 40709996, 2025). "SELL, PTPRC, IL7R, CCR7, and KLRB1 were able to distinguish leukemia cells from normal cells well, with AUC values higher than 0.970." (PMID 38165493, 2024). "In this context, a fully human anti-IL7R antibody, which impaired IL-7/IL7R-mediated signalling, making T-ALL cells sensitive to chemotherapy, and promoting leukemia cell killing through a NK-mediated cytotoxicity, was generated." (PMID 36624522, 2023). "B12 can inhibit IL-7R-mediated signaling pathway, promoting T-ALL cell death in vitro and delay the progression of leukemia in vivo, which has obvious preclinical value." (PMID 36142322, 2022). "High IL-7R signaling creates an oncogenic environment, and transplanted murine thymocytes with a mutant Il7r are able to induce an ETP-ALL–like leukemia in recipient mice." (PMID 35536646, 2022). "Our work highlights a synergy between mutant IL7R and Myc in inducing T-ALL and demonstrates that mutant IL7R enriches for leukemia propagating potential." (PMID 35581375, 2022). "IKZF1 and IL7R synergistically activated downstream JAK/STAT5 and PI3K/Akt/mTOR signaling pathways to promote leukemia." (PMID 35419036, 2022). "IL-7 and IL-7R activate three main signaling networks: STAT5, PI3K/AKT/mTOR and MEK/ERK, leading to leukemia cell progression and survival, also with regard to T-ALL." (PMID 34026651, 2021). "B12 impairs IL-7R-mediated signaling and is able to promote T-ALL cell death in vitro and delay leukemia progression in vivo, demonstrating obvious pre-clinical value." (PMID 30850736, 2019). "While SH2B3 suppresses IL-7R/JAK/STAT signaling to restrict pro-/pre-B progenitor expansion and leukemia development, Ikaros plays an essential role in lymphocyte development and functions as a tumor suppressor in leukemia." (PMID 27322554, 2016).